CCL22 (C-C motif chemokine ligand 22)
Diseases named in the same sentence as CCL22 in open-access papers (continued):
Sharing a sentence is not in itself a finding about the gene and the disease.
tumor (continued). "Co-expression of CCR4 improved the homing ability of anti-CD30 CAR-T cells to Hodgkin tumor sites by enhancing their migration toward CCR4 ligands CCL17 and CCL22, which are highly expressed in the tumor microenvironment." (PMID 41181132, 2025). "Accordingly, we observed that tumor DC2s and moDCs share a similar transcriptome, including the expression of Treg-recruiting genes such as Ccl22 and Ccl17." (PMID 40146036, 2025). "Specifically, Bcor−/−; TCL1 malignant cells showed upregulation of Ccl17 and Ccl22 chemokines that attract regulatory T (Treg) and Th2 cells in tumor microenvironment (TME)." (PMID 40113912, 2025). "To elucidate the CCL22-expression on the mRNA level, we performed a quantitative RT-PCR of tumor cells after coculture with PBMCs." (PMID 39232378, 2024). "The expression of CCL17 and CCL22 is increased in the lung, liver, and brain of tumor-bearing nude mice with an increased malignancy phenotype of cancer cells." (PMID 39114657, 2024). "The interaction between myeloid cells and tumor cells triggers the production of CCL22, a CCR4 ligand, facilitating Treg recruitment and the suppression of conventional T-cell responses." (PMID 39000453, 2024). "CCL22 is a key player in cancer-related immune responses, primarily affecting regulatory T cells (Treg) and their interactions with dendritic cells in the tumor microenvironment." (PMID 38791448, 2024). "In summary, immune cells and tumor cells seem to cooperate in driving the production of CCL22 via proinflammatory cytokines." (PMID 39232378, 2024). "HCC patients with positive expression of CCL22 or PD‐L1 were positively correlated with more aggressive tumor behaviors and worse prognosis." (PMID 39072947, 2024). "CCL22 controls T cell immunity by recruiting T regs to tumor tissues and by promoting the formation of DC‐T reg contacts in lymph nodes." (PMID 39508721, 2024). "Abundant CCL22-expression by tumor cells has been reported following combined crosstalk with NK cells and macrophages via the proinflammatory cytokines IFN-γ, TNF-α and IL1β." (PMID 39232378, 2024). "CCL22 is highly expressed in several types of tumors and is known to recruit Tregs into tumor tissue." (PMID 39513112, 2024). "CCL22 produced by tumor derived macrophages and CCL17 regulate the infiltration of Tregs into the tumor sites." (PMID 38571964, 2024). "In a different study, NK cells were engineered to overexpress CCR2B and CCR4 to induce migration toward CCL2- and CCL22-expressing tumor cells, respectively." (PMID 39114657, 2024). "Type I interferon can block the chemokine CCL22 that attracts Tregs, thus helping to limit Treg recruitment by tumours and inhibit tumour progression." (PMID 38475858, 2024). "In contrast, the culture of malignant cells in PBMC-SN resulted in reduced levels of CCL22, indicating consumption or uptake by tumor cells or enhanced degradation of the protein." (PMID 39232378, 2024). "Elevated levels of CCL22 have been observed in the tumor microenvironment of melanoma and other tumors." (PMID 38928238, 2024). "Macrophage secretion of cytokines, including CCL22, attracts Treg to the tumor microenvironment, thereby hampering cytotoxic T cell activation and promoting tumor development." (PMID 38730724, 2024). "CCR4 induces chemotaxis in response to its target chemokines, CCL17 and CCL22, which are often upregulated in tumor microenvironments." (PMID 38254876, 2024). "Since CCL22 can only exert its effect as a Treg-attracting chemokine extracellularly, impeded secretion results in less Treg invasion and thus reduced tumor progression." (PMID 39232378, 2024). "Taken together, we found CCL22 to be expressed by EC cells, distant myometrial M1-macrophages, and in areas of the stroma located close to the tumor." (PMID 39232378, 2024). "In conjunction with IDO1 expression on the tumor cell side, CCL22-positive cells create local environments that protect tumor cells from immune cell attacks." (PMID 39639005, 2024).
tumor (continued). "Elevated CCL22 staining in tumor cells and CCL22-positive M1-macrophages in tumordistant areas were significantly associated with increased overall survival (OS)." (PMID 39232378, 2024). "Recent studies have shown that TAM-derived CCL22 can activate the FAK signaling axis in tumor cells, thereby promoting ESCC progression." (PMID 38562942, 2024). "It was also found that the combined function of IFN-γ, TNF-α, and IL-1β will stimulate CCL22 secretion by tumor cells." (PMID 39003350, 2024). "On the other hand, CD8+T cells can induce in situ proliferation of Tregs, which can also recruit Tregs into the tumor by secreting CCL22 and binding with CCR4 on the surface of Tregs." (PMID 38390329, 2024). "CCL22 plays a role in shaping the immune response within the tumor microenvironment by recruiting immunosuppressive cell populations, such as Tregs." (PMID 38928238, 2024). "Recent studies have illuminated the role of CCL22, particularly its elevated expression in TAMs, in activating diverse signaling pathways that enhance the metastatic capabilities of tumor cells." (PMID 39286635, 2024). "Multiple studies have demonstrated the ability of mRNA vaccines, in situ anti-tumor vaccines, CCL22-based peptide vaccines, and novel bioactive nanovaccines to enhance the immune microenvironment of tumors." (PMID 38380323, 2024). "Although the role of CCL22 has already been documented in several tumor types, data in EC are missing." (PMID 39232378, 2024). "C–C motif chemokine ligand 22 (CCL22) displays chemotactic activity, attracting T regs to the tumor tissue, and plays a significant role in suppressing T cell immunity, it has demonstrated potential as a target in preclinical models." (PMID 38430429, 2024). "The immunosuppressive setting is controlled by different cellular elements and processes involving Tregs migrating into OC primarily due to the action of C-C motif chemokine 22 (CCL22) in the tumor microenvironment." (PMID 39200270, 2024). "The chemokine CCL22 is recognized for recruiting immunosuppressive regulatory T-cells (Treg) that contribute to disease progression in various tumor entities helping them to evade the host immune response." (PMID 39232378, 2024). "Culture of tumor cells in cell-free SN of PBMCs resulted in a reduced CCL22 level, suggesting either a consumption or uptake of CCL22 by tumor cells or an enhanced degradation of protein in the presence of tumor cells." (PMID 39232378, 2024). "Both CXCL1 and CXCL3 genes, along with CCL22, are involved in the chemotaxis of tumor cells and stromal cells within the surrounding microenvironment, which is essential in tumor dissemination during progression and metastasis." (PMID 39408697, 2024). "Researchers reported that CCL22 can recruit CD8+T lymphocytes in the tumor microenvironment and inhibit tumor growth." (PMID 36969873, 2023). "It has also been shown, consistent with our findings, that high levels of chemokines CCL4, CCL22, and CCL28 in pre-treatment tumor specimens were associated with worse patient overall survival after immunotherapy in RCC." (PMID 38067341, 2023). "We further identified the time course of serum CCL22 change from the beginning of tumor inoculation." (PMID 36969873, 2023). "Tumour-infiltrating macrophages and tumour cells can produce chemokine ligand 22 (CCL22), which attracts cells expressing CCR4 to the tumour tissue." (PMID 38259489, 2023). "In other work, vaccination with CCL22-derived peptides in in vivo mouse models of cancer induced CCL22-specific T-cell responses that slowed tumor growth and extended survival." (PMID 36175673, 2023). "CCL22, which is produced and increased by ovarian TAMs, can stimulate Treg cell trafficking to the tumor." (PMID 37298230, 2023). "CCL17, CCL19, and CCL22 have been shown to mediate DC trafficking between the tumor and draining lymph nodes while promoting the activation of tumor-specific T cells." (PMID 37532692, 2023).
tumor (continued). "As expected, we found that the cell densities of CD3/CD8 and CD56/CCL22 were significantly higher in the tumour region of the recurrent group." (PMID 37488671, 2023). "At the same time, CCL22 can further stimulate Treg to secrete IL-10, which can polarize macrophages to M2 type and promote tumor growth." (PMID 36969873, 2023). "Since, CCL22 was the only chemokine which showed significant change in the expression level after MIP treatment, we next searched for the cellular source/s of CCL22 in the tumor infiltrating leukocytes (TILs)." (PMID 37122749, 2023). "In malignant pleural effusion, macrophage-derived CCL22 promotes an immunosuppressive tumor microenvironment via IL-8." (PMID 36334221, 2023). "Since tumor cells usually was the largest proportion cell type in tumor tissues, tumor-derived CCL22 cannot be ignored." (PMID 36969873, 2023). "In this study, the proportion of CCL22 transcription level in tumor cells was similar to that in macrophages." (PMID 36969873, 2023). "The Ccl22 transcription level and expression level of in the tumor were analyzed on the 40 DPT, the transcription level of Ccl22 were significantly decreased." (PMID 36969873, 2023). "An important article in 2004 has demonstrated that neutralizing CCL22 can inhibit Treg infiltration and further inhibit tumor growth." (PMID 36969873, 2023). "Prior studies have reported that IFN-α negatively regulates CCL22 expression in tumor infiltrating leukocytes." (PMID 37122749, 2023). "Treg cells are recruited to the tumor foci by chemokines such as CCL22 in the tumor microenvironment, while CD4+ and CD25+ T cells are converted to Treg cells by specific cytokines." (PMID 36923251, 2023). "As CCR4 is the shared receptor for both CCL17 and CCL22 and is reported to be overexpressed in tumor cells, we next examined its expression on the membrane of CRC cells and reproducibly detected strong signals in the isolated membrane fractions." (PMID 37658050, 2023). "CCL22 and CCL17 are released by tumor cells and tumor-associated macrophages, attracting CCR4+ Tregs to the tumor site." (PMID 35222362, 2022). "Enhanced expression of CCL22 in the tumor tissues of patients with hepatocellular carcinoma was reported in some studies and was associated with accelerated tumor growth." (PMID 36555280, 2022). "Specifically, in HCC, Treg cells can be recruited into tumour tissues, and this accumulation is mainly mediated by the chemokine CCL22, which is secreted by intratumoural DCs." (PMID 36195857, 2022). "Other reports show that CCL22 is mainly from tumor-infiltrating cells, such as dendritic cells (DCs) or macrophages." (PMID 35805111, 2022). "CCL22 is secreted by tumor cells, dendritic cells, and macrophages and regulates the differentiation, proliferation, and localization of lymphocytes and dendritic cells through binding to the CCR4 receptor on the surface of immune cells." (PMID 35396377, 2022). "Our study found that the high-CCL22-expression subgroup had a higher immune/stromal/estimate score and lower tumor purity." (PMID 35295948, 2022). "In the TME, CCL22 mediates Treg infiltration into the tumor tissue through CCR4, facilitating tumor immunosuppression and leading to inhibition of antitumor immunity." (PMID 35962191, 2022). "Macrophages secrete CCL22 to induce Treg migration to the tumor area and inhibit the activation of CD4 (+) CD25 (-) T cells, resulting in poor prognosis in the high-risk group." (PMID 36324575, 2022). "The environment of tumors such as ovarian cancer and Hodgkin lymphoma contains high concentrations of CC-chemokine ligand 22 (CCL22), which is secreted from both tumor macrophages and tumor cells." (PMID 36419156, 2022). "Our finding of the phosphorylation-dependent adaptor function of DGKα revealed an important mechanism by which the CCR4/DGKα/FAK complex coordinately regulates CCL22-induced tumor metastasis." (PMID 35962191, 2022).
tumor (continued). "CCL17 and CCL22 were responsible for recruiting Treg into the tumor niche in a CCR4-dependent manner, leading to immune evasion and cancer metastasis." (PMID 36380313, 2022). "CCL22 is a chemokine that regulates Treg, and TAM-derived CCL22 promotes Treg recruitment at tumor sites, which inhibits cytotoxic T cell responses." (PMID 36510315, 2022). "It was previously reported that M2 macrophages can induce Treg infiltration into the tumor microenvironment, inhibit T-cell immunity, and promote tumor growth by overexpressing CCL1 or CCL22." (PMID 35326602, 2022). "The chemokines CCL17 and CCL22, which are secreted by tumor cells and macrophages, have been reported as key factors in the recruitment of Tregs via the CCR4 receptor in ESCC." (PMID 36698392, 2022). "The high expression of chemotactic factor CCL22 and CCL22 can recruit regulatory T cells (Treg) to the tumor site of NSCLC." (PMID 35176085, 2022). "For instance, CCL22 (C-C motif chemokine 22) controls T cell immunity by recruiting regulatory T cells to the tumor tissue and promoting regulatory T cell communication with dendritic cells in TME." (PMID 36146599, 2022). "Recruitment of Tregs to the TME occurs by binding of C-C chemokine receptor type 4 (CCR4) on the T cell surface by macrophage-derived chemokine (MDC/CCL22) produced by the tumor." (PMID 36092724, 2022). "Tregs are recruited through the binding of CCR4 on Tregs surface and CCL22 released by GBM tumor cells and CD163+ TAMs, induced by tumor-derived CCL20 and osteoprotegerin." (PMID 35269652, 2022). "Both CCL22 and CCL17, which are produced by tumor cells, tumor-associated macrophages, and dendritic cells, establish a concentration gradient around the tumor mass and attract CCR4+ Tregs to maintain immunological homeostasis in the tumor vicinity." (PMID 35222362, 2022). "In malignancy, CCR4-expressing Treg interacts with CCL17 and CCL22-secreting tumor cells, with resultant impairment of host antitumor immunity." (PMID 35464471, 2022). "For example, Curiel and colleagues provide evidence that T regs migrate to and accumulate in the tumor tissue in a CCL22-dependent manner, contributing to an immunosuppressive environment." (PMID 35805111, 2022). "CCL22 was differentially expressed in the subgroup analyses according to tumor M stage in TCGA COAD." (PMID 35295948, 2022). "CCL22 drives the recruitment of Treg cells to the tumor tissue and contributes to an immunosuppressive microenvironment, thus potentially impairing antitumor immunity." (PMID 35962191, 2022). "CCL22-induced addiction to FAK was demonstrated by the persistent suppression of tumor progression upon FAK-specific inhibition." (PMID 35962191, 2022). "CCL22 released by tumor cells and tumor-infiltrating macrophages attracts the recruitment of Tregs through the combination of C–C chemokine receptor type 4 (CCR4)." (PMID 36119033, 2022). "The functional role of CCL22 in cancer immunity involves recruiting Tregs to the tumor stroma by binding to its cognate receptor CCR4." (PMID 35960749, 2022). "In fact, both human and mouse CCL22 expression was observed, and this expression was localized, respectively, to tumor cells and regions of host cell infiltration." (PMID 35025968, 2022). "Previous research indicated that CCL22 is abundantly expressed that induces tumorigenesis and tumor progression in different types of cancers such as cervical cancer, breast cancer, and ovarian carcinoma." (PMID 35396377, 2022). "Summary of the involvement of CCL2, CCL17, and CCL22 in different health problems in the cases of pain, immunity, and tumor studies." (PMID 36555280, 2022). "Tumor-associated macrophage (TAM)-induced peritoneal mesothelial cell fibrosis, CCL22/CCXR4 axis, and HIF-1α have been reported to facilitate tumor cell invasion." (PMID 35740397, 2022). "FOXP3+ cells were seen in the vicinity of CCL22-positivity, which had a punctate pattern throughout the tumor." (PMID 35025968, 2022).
tumor (continued). "CCL22 is a chemokine that is highly expressed in tumors, and promotes tumor growth, in addition to playing a role in tumor-related immunosuppression." (PMID 35464849, 2022). "An immune-suppressive tumor environment constituted by Tregs and M2 macrophages along with immunosuppressive mediators such as CCL17, CCL18, CCL22, and PD-L1 can assist tumor development and progression." (PMID 34937192, 2021). "Apart from the tumor-infiltrating CD8+ T cells (major in hot tumor), tumor cells, M2-like TAMs, and MDSCs can facilitate Treg tumor infiltration by increasing CCL22 secretion in cold tumors." (PMID 34138315, 2021). "To verify the previously reported results, we performed immunohistochemical staining using eight paraffin-embedded tumor tissue samples to investigate the expression of CCL22, GATA-3, and IL4." (PMID 34391381, 2021). "Previous studies have shown that Treg migration and infiltration into various tumour tissues appear to be dependent on the expression of the CCR4 ligand (CCL22) produced by tumour cells or infiltrating macrophages." (PMID 33654093, 2021). "These genes included C–C chemokine ligand 5 (CCL5) and C–C chemokine ligand 22 (CCL22) which have been shown to attract suppressive immune cells to tumours." (PMID 34602068, 2021). "The chemokine ligand 22 of the C-C motif (CCL22) is a member of the family of chemokines secreted by macrophages and tumor cells and binds to the chemokine [C-C motif] receptor 4 (CCR4)." (PMID 34452282, 2021). "For example, IL-6, VEGF, CCL22 and/or PGE2 produced by tumor cells recruited tumor-associated macrophages, which in turn produced IL-23 and maintained suppressive Treg activity in the TME." (PMID 33418929, 2021). "They showed that the expansion of TAMs with M2 phenotype promote tumor growth and invasiveness through the release of CCL22." (PMID 33737571, 2021). "Substantial reductions in suppressive cytokines, including CCL2, CCL17, CCL22 and IL-10, were also noted and were associated with reduced CD4+ CD25+ Foxp3+ Treg recruitment in the tumour." (PMID 33513866, 2021). "Both ligands but mostly CCL22 are largely involved in directing the recruitment and induction of suppressive function of Tregs at the tumor site." (PMID 34944943, 2021). "Secretion of the regulatory T cell recruiting cytokine, CCL22, was also highly upregulated upon monocyte addition to all tumor spheroids." (PMID 34451433, 2021). "High intratumoral concentrations of CCL22 have been reported; the source of CCL22 within the tumor stroma is, however, an area of debate, with both tumor and DCs being reported." (PMID 34503058, 2021). "On the other hand, studies show that CCL-22 leads to the recruitment of Treg into the tumor tissues, and suppression of intratumoral CCL-22 by IFN-I inhibits migration of regulatory T cells and blocks cancer progression." (PMID 34620867, 2021). "Analogously, macrophages secrete CCL22 to induce Tregs to migrate into tumor region in ovarian cancer, inhibiting T cell immunity and promoting tumor growth." (PMID 34625124, 2021). "TAMs can produce various chemokines, such as CCL17, CCL18, and CCL22, which attract Treg cells to tumor sites, thereby impeding cytotoxic T cell activation." (PMID 33568167, 2021). "Curcumin significantly decreased CCL22 levels in supernatants of tumor samples compared to the untreated controls." (PMID 33809574, 2021). "In PCa TAMs express CCL22, which potentiates tumor migration and invasion and traffics T regulatory cells (Tregs) to the site of the tumor." (PMID 33800156, 2021). "Tumor cells and cells in the tumor microenvironment secrete high amounts of CCL22, a ligand for CCR4, in various cancers." (PMID 33679808, 2021). "In conclusion, L1CAM promotes tumorigenesis and induces CCL22 secretion in ESCC tumor cells via PI3K/Akt and NF-κB." (PMID 33710805, 2021).